BIRC5 (baculoviral IAP repeat containing 5)
Diseases named in the same sentence as BIRC5 in open-access papers (continued):
Sharing a sentence is not in itself a finding about the gene and the disease.
lung adenocarcinoma (continued). "We also found that the ratio of miR-195 to BIRC5 in patient tumors is associated with overall survival and recurrence-free survival of lung adenocarcinoma patients, but not lung squamous cell carcinoma patients." (PMID 29416000, 2018). "Therefore, we speculated whether KLF2 played a role in lung adenocarcinoma by regulating BIRC5 expression." (PMID 35322532, 2022). "Additionally, KLF2 suppressed BIRC5 to promote the radiosensitivity of lung adenocarcinoma cells." (PMID 35322532, 2022). "Moreover, BIRC5 up-regulation was previously documented in lung adenocarcinoma cells and tissues, wherein = radiosensitivity could affect the dependence on BIRC5 expression." (PMID 34372869, 2021). "Cell cycle-related genes (BIRC5, OIP5, and CDCA3, etc.)were specifically upregulated in PTPRT-low lung adenocarcinoma (LUAD)." (PMID 38216925, 2024). "In lung adenocarcinoma (LUAD), BIRC5 protein expression was significantly higher in tumor cell lines compared to normal lung epithelial cells." (PMID 39703228, 2024). "The genetic alterations and gene expression changes in the BIRC5, HIF1A, and FLT4 oncogenes in lung adenocarcinoma (LUAD) were analyzed using muTarget software." (PMID 37509650, 2023). "It was found that KLF2 and BIRC5 were negatively correlated in lung adenocarcinoma through GEPIA2, and BIRC5 was significantly highly expressed in lung adenocarcinoma." (PMID 35322532, 2022). "In lung adenocarcinoma cells, miR-101 can enhance LUAD cell sensitivity to radiotherapy by regulating the expression of baculoviral IAP repeat containing 5 (BIRC5)." (PMID 36497343, 2022). "Data obtained in our study demonstrated that miR‐126‐5p‐mediated EZH2 exerted suppressive effects on proliferation, invasion and inducing effect on lung adenocarcinoma cell radiosensitivity and apoptosis via interaction between KLF2 and BIRC5." (PMID 35322532, 2022). "Among them, CRABP2, KAT2A, BIRC5, ABCC3, PLK1, IGHG1, and EPCAM were upregulated in lung adenocarcinoma samples, while FABP4 was downregulated in lung adenocarcinoma samples." (PMID 35909589, 2022). "In lung adenocarcinoma, down-regulated lncRNA LINC00857 inhibited the expression of BIRC5 by inhibiting the enrichment of NF-κB1 in the promoter region of BIRC5, thereby enhancing radiosensitivity." (PMID 35600868, 2022). "Among patients with lung adenocarcinoma (LUAD), the expression level of BIRC5 was higher than that in normal samples, and the expression of BIRC1 and BIRC5 significantly varied in different stages." (PMID 34925455, 2021). "The presence of NPs under magnetic field reduced the BIRC5 expression and elevated the DR5 expression in lung adenocarcinoma cells." (PMID 34372869, 2021). "Through clustering of a genome-scale co-expression network, lung adenocarcinoma modules were revealed; in few modules, the genes such as DLGAP5 and BIRC5 are present that play a crucial role in cell cycle progression." (PMID 28808310, 2017). "The intersections of LPS induction-related genes, lung adenocarcinoma differential genes, and univariate cox genes were obtained, and five genes (TNS4, PRC1, MKI67, CDKN3, BIRC5) were obtained, which were defined as the characteristic genes associated with LPS induction." (PMID 40697537, 2025). "Finally, SFTPA1, PLXNB3, BIRC5, CBLC, and ACVRL1 were screened out based on the intersection between the top 10 differentially expressed genes in lung adenocarcinoma (LUAD) and lung squamous cell carcinoma (LUSC)." (PMID 34181042, 2022). "Therefore, it can be concluded that miR‐126‐5p facilitated proliferation, invasion and radiosensitivity of lung adenocarcinoma cells and repressed apoptosis by targeting EZH2 via interaction between KLF2 and BIRC5." (PMID 35322532, 2022). "Expanding on this, our findings displayed that Fe3O4 MNPs could reduce the BIRC5 expression in lung adenocarcinoma cells by delivering siBIRC5 and AS-ODN into lung adenocarcinoma cells simultaneously." (PMID 34372869, 2021).
lung adenocarcinoma (continued). "In addition, there are some genes in other modules that can have very important roles in lung adenocarcinoma, namely DLGAP5, BIRC5, PSMD2, Src, TTK, SENP2, PSMD2, DOK2, FUS among others." (PMID 23874428, 2013). "And compared with normal tissues, BIRC5 expression is significantly higher in tumor tissues samples from patients with 20 out of 33 tumor types, including bladder urothelial carcinoma (BLCA), BRCA, HNSC, lung adenocarcinoma(LUAD), lung squamous cell carcinoma (LUSC) and READ." (PMID 37661276, 2023).
hepatocellular carcinoma (33 papers, 2013 to 2025). A malignant tumor that arises from hepatocytes. "This research aimed to assess the diagnostic capacity of anti-BIRC5 autoantibody in detecting AFP-negative hepatocellular carcinoma (ANHCC)." (PMID 38832035, 2024). "Lastly, the diagnostic usefulness of the anti-BIRC5 autoantibody for hepatocellular carcinoma (HCC) was evaluated by ELISA in a cohort consisting of an additional 149 AFP-positive hepatocellular carcinoma samples (APHCCs), 95 ANHCCs and 244 NCs." (PMID 38832035, 2024). "Nevertheless, UDCA inhibited the expression of cell cycle-related genes and the repression effect was enhanced with a time increase (PLK1, UBE2C, BUB1, CDC20, BIRC5, p <0.001) in hepatoma cell lines SNU387." (PMID 38255993, 2024). "Reportedly, silencing of AFP can be achieved in the hepatoma cell line HepG2 by reducing BIRC5 (survivin) mRNA expression." (PMID 38202502, 2023). "While in rat hepatoma cell lines, BIRC5 expression promoted resistance to cisplatin-induced apoptosis through PI3K-dependent survivin expression." (PMID 37248280, 2023). "Aberrant expression of these genes also contributes to the progression of diverse cancers: for instance, OCT4 elevates the promoter activity of BIRC5, contributing to the progression of hepatocellular carcinoma." (PMID 35309512, 2022). "CCNB1 and BIRC5 have been reported to be related to the immune infiltration of hepatocellular carcinoma, and their expressions are positively correlated with the infiltration levels of CD4 + T cells and dendritic cells, respectively." (PMID 36175893, 2022). "In a recent study on hepatocellular cancer, BIRC5 was found to be one of the top scorers with the best prognostic value that high expression of BIRC5 significantly correlated to weaker immune cells infiltrations and poorer overall survival." (PMID 36046648, 2022). "It is reported that the increased expression of BIRC5 in hepatocellular carcinoma inhibits the apoptosis of tumor cells, promotes the proliferation of tumor cells, and increases the resistance of hepatocellular carcinoma cells to radiotherapy and chemotherapy." (PMID 34616672, 2021). "In hepatocellular carcinoma cells, Oct3/4 was shown to upregulate BIRC5 (survivin) and CCND1 expression by increasing their promoter activity, thereby promoting cell proliferation and resisting cell apoptosis." (PMID 26483189, 2015). "BIRC5 is known to be crucial for cell division and may prevent apoptosis, while the overexpression of BIRC5 encourages tumor growth in hepatocellular carcinoma." (PMID 37509299, 2023). "High expression of BIRC5 was found to indicate poor prognosis in hepatocellular carcinoma." (PMID 35237298, 2021). "In hepatocellular carcinoma, down-regulation of BIRC5 could induce cancer cell apoptosis and cell cycle arrest." (PMID 32662515, 2020). "BIRC5 has been shown to be a miR-203 target in leukemia and hepatocellular carcinoma." (PMID 30241553, 2018). "The baculoviral IAP repeat containing 5 (BIRC5) related to epithelial-mesenchymal transition (EMT) plays a crucial role in the pathogenesis of hepatocellular carcinoma (HCC)." (PMID 34112092, 2021). "In prediction models for autophagy-related genes, multiple autophagy genes are involved, such as ATG10, ATIC, BIRC5, and CAPN10, and their changes effectively affect the survival time of hepatocellular carcinoma patients." (PMID 39502521, 2024). "We also used a GSE84402 dataset to validate the mRNA expression levels of IGF1, CDKN2A, BIRC5, and SPP1 in hepatocellular carcinoma tissues and adjacent tissues." (PMID 39042294, 2024).
hepatocellular carcinoma (continued). "In vitro studies have suggested that BIRC5/Survivin could be implicated in chemotherapy resistance of Irinotecan in colon adenocarcinoma (COAD), Oxaliplatin in esophageal squamous and esophageal adenocarcinoma (ESCA) and Cisplatin in hepatocellular carcinoma (LIHC)." (PMID 35331169, 2022). "The results of immunohistochemistry showed that the protein expression levels of HDAC1, BIRC5, SPP1, STC2 in hepatocellular carcinoma tissues were higher than those in normal tissues." (PMID 34616672, 2021). "After univariate cox regression analysis, lasso analysis and multivariate cox analysis, a five-gene signature (including HDAC1, BIRC5, SPP1, STC2, NR6A1) was constructed to predict the prognosis of hepatocellular carcinoma." (PMID 34616672, 2021). "OCT4 can upregulate the expression of BIRC5 and CCND1 by enhancing its promoter activity, these factors jointly promote the proliferation of liver cancer cells and aggravate prognosis of patients with Hepatocellular Carcinoma (HCC)." (PMID 34087900, 2021). "A number of the miRNAs in this signature have been previously characterized in cervical cancer and other diseases, such as miR-218, which downregulates survivin (BIRC5) in nasopharyngeal carcinoma, and miR-21, which regulates PTEN expression in hepatocellular carcinoma." (PMID 25880806, 2015). "By manipulating OCT4 and BIRC5 expression in hepatocellular carcinoma (HCC) cell lines, the regulatory mechanism of OCT4 on BIRC5 and CCND1 were investigated." (PMID 23433354, 2013). "BIRC5, SPINK5, SPP1, CACYBP, RAET1E, and NR0B1 were significantly up-regulated, and S100A8 was significantly down-regulated in hepatocellular carcinoma samples based on TCGA-HCC dataset." (PMID 33568167, 2021).
prostate carcinoma (33 papers, 2010 to 2025). A carcinoma that arises from epithelial cells of the prostate gland. "Univariate regression analysis showed that BIRC5 was a high-risk factor (HR = 1.9) of prostate cancer and its p-value was the smallest among analyzed factors." (PMID 34490029, 2021). "Univariate analysis showed that BIRC5 is a high-risk predictor in prostate cancer and its p-value was the smallest compared with other factors." (PMID 34490029, 2021). "Other genes that have been implicated in prostate cancer include baculoviral IAP repeat containing 5 (BIRC5), also known as survivin and ERG." (PMID 27144529, 2016). "To determine whether urinary EVs could be used to examine other genes associated with prostate cancer we investigated the differential expression of androgen receptor (AR), BIRC5, ERG, PCA3, TMPRSS2:ERG and TMPRSS2 in Bx Pos versus Bx Neg patients." (PMID 27144529, 2016). "We had previously shown the effectiveness of a PPRH against BIRC5 (survivin) in a xenograft model using prostate cancer cells." (PMID 37108234, 2023). "Overexpression of BIRC5/survivin prevents apoptosis in prostate cancer cells and is a positive factor in their progression and survival." (PMID 35317831, 2022). "BIRC5/survivin downregulation using siRNA sensitizes prostate cancer cells to apoptosis and autophagy." (PMID 35317831, 2022). "The findings showed that the migration rate of cells was significantly reduced after knocking down BIRC5 in prostate cancer cells DU145 and PC-3 at 24 and 48h compared with that in the control group." (PMID 34490029, 2021). "In summary, the findings of this study showed that BIRC5 is highly expressed in prostate cancer tissues, and knocking down BIRC5 can significantly inhibit proliferation and migration rate of prostate cancer cells in vitro." (PMID 34490029, 2021). "After knocking down BIRC5 in prostate cancer cells, CCK-8 assay was used to determine the effect of BIRC5 on proliferation of prostate cancer cells." (PMID 34490029, 2021). "The in vitro experiments in the current study showed that BIRC5 is highly expressed in prostate cancer tissues, and it modulates proliferation and migration rate of prostate cancer cells." (PMID 34490029, 2021). "BIRC5, as an immune-related gene in the prediction model, was up-regulated in 87.5% of prostate cancer tissues." (PMID 34490029, 2021). "In recent years, considerable evidence suggested that abnormal expression of BIRC5 is involved in the progression of various cancers, including lung, breast, colon, pancreatic, and prostate cancers." (PMID 34330893, 2021). "Recent data obtained on a very large number of prostate cancer samples demonstrate that BIRC5 mRNA increased in prostate cancer and prostate cancer metastases compared to tissues from healthy donors or from adjacent normal prostate tissues combined." (PMID 33413657, 2021). "Studies have shown that BIRC5 is a biomarker for Oral Squamous Cell Carcinoma as well as breast, liver and prostate cancer." (PMID 32266115, 2020). "This was also the case when comparing BIRC5 expression in prostate cancers with the corresponding normal adjacent tissues from the same patient using paired analysis (p = 0.0126, n = 58 patients)." (PMID 32094363, 2020). "Pooled analysis revealed a significant increase of BIRC5 mRNA in prostate cancers (p < 0.05) and prostate cancer metastases (p < 0.0001) compared to tissues from healthy donors or from adjacent normal prostate tissues combined (=no tumor)." (PMID 32094363, 2020). "In total, prostate cancers from 41 out of 58 matched patients (70.7%) showed increased BIRC5 expression compared to corresponding normal adjacent tissues." (PMID 32094363, 2020).
prostate carcinoma (continued). "To further confirm that the pro-apoptotic effect of miR-34a is mediated through the suppression of BIRC5 in Ras signaling-activated prostate cancer cells, we overexpressed BIRC5 in RasB1 cells harboring the miR-34a precursor." (PMID 25436980, 2015). "In prostate cancer patients, we found that BIRC5 levels were positively correlated with a Ras signaling signature expression." (PMID 25436980, 2015). "We explored the relevance of this finding by studying the expression of BIRC5 in a public human prostate cancer dataset." (PMID 25436980, 2015). "To examine the relation between miR-34a and BIRC5 expression in prostate cancer progression, we employed a Pearson coefficient correction analysis and found that the mean expression of BIRC5 was significantly inversely correlated to miR-34a expression." (PMID 25436980, 2015). "As BIRC2 (cIAP1), BIRC4 (XIAP) and BIRC5 (survivin) tended to be co-upregulated in prostate cancer in addition to BIRC6, simultaneous targeting of BIRC6 plus one of these IAP members was more likely to give superior anti-cancer effects." (PMID 25071009, 2014). "Remarkably, BIRC5 expression showed a highly significant increase in both primary (p = 5.26E-14) and especially metastatic (p = 1.07E-11) prostate cancer." (PMID 25248616, 2014). "BIRC5 is expressed in the majority of human cancers, including those of squamous histology, e.g., head and neck, laryngeal, esophageal, lung, ovarian, gastric, colorectal, bladder, pancreatic, and prostate cancer, as well as melanoma and soft tissue sarcomas." (PMID 35326407, 2022). "BIRC5 in the cytoplasm then interacts with XIAP (also upregulated in prostate cancer)." (PMID 33413657, 2021). "Prostate cancer is another major health concern where BIRC5 has been studied and described." (PMID 33413657, 2021). "In addition, survival analysis showed that BIRC5 is correlated with the prognosis of prostate cancer (p = 0.0005852)." (PMID 34490029, 2021). "Using the GEO GDS2545 dataset, we compared mRNA expression of the survivin gene BIRC5 in normal prostate tissue from healthy donors, normal prostate tissues adjacent to primary prostate cancer, primary cancers, and prostate cancer metastasis in an unpaired fashion." (PMID 32094363, 2020). "BIRC5 has been previously found to be the target gene of miR-34a in breast and colorectal cancers, and our data further confirmed this relation in prostate cancer." (PMID 25436980, 2015). "An important anti-apoptotic protein, BIRC5 (also known as Survivin) was found to contain a miR-34a binding region, and which was down- and up-regulated when using a miR-34a precursor and inhibitor in Ras-activated prostate cancer cells, respectively." (PMID 25436980, 2015). "Moreover, reduced expression of survivin (BIRC5) in ENL treated LNCaP cells further supports the caspase –mediated apoptosis pathways as one of the targets for the lignan action in prostate cancer." (PMID 22254011, 2010). "Moreover, survival analysis showed that BIRC5 is correlated with the prognosis of prostate cancer." (PMID 34490029, 2021). "The data of the TCGA database demonstrated that those PCa patients who showed low SERPINB5 and high BIRC5 transcript expression were characterized by a reduced disease-free survival rate, thereby highlighting the clinical relevance of the activation of the NFκB pathway in human prostate cancer." (PMID 32640711, 2020). "Our data show that the bone metastasis and anti-apoptotic effects found in Ras signaling-activated prostate cancer cells require miR-34a deficiency, which in turn aids in cell survival by activating the WNT and anti-apoptotic signaling pathways thereby inducing TCF7 and BIRC5 expressions." (PMID 25436980, 2015). "The findings showed that the proliferation rate of prostate cancer cells DU145 and PC-3 was significantly lower after knocking down BIRC5 compared with that of the control group." (PMID 34490029, 2021).
prostate carcinoma (continued). "The use of EVs was also examined as a potential platform to non-invasively differentiate Bx Pos versus Bx Neg patients via the detection of known prostate cancer genes TMPRSS2:ERG, BIRC5, ERG, PCA3 and TMPRSS2." (PMID 27144529, 2016). "Besides, two potential therapeutic targets, BIRC5 and RHOC, were identified by us in prostate cancer." (PMID 36439479, 2022). "In addition to that, we observed a correlation between Ras activation, BIRC5, and TCF7 expression in prostate cancer samples." (PMID 25436980, 2015). "Thus, the drugs targeting BIRC5 and RHOC may be potential targets in the treatment of prostate cancer." (PMID 36439479, 2022). "In addition, in prostate cancer, CKAP2, LASP1, BIRC5, WASF1, ASAP1 and RUNX2 mRNAs were recently identified as new miR-203 targets, suggesting that miR-203 could be a new prognostic marker and a therapeutic target in metastasis of prostate cancer." (PMID 23285092, 2012). "This indicats that tissues from non-tumor prostate tissues, primary and metastatic stage prostate cancer tissues dataset, with down-regulated KRAS signatures, have more TCF7 and BIRC5 expression." (PMID 25436980, 2015).